CXCR4 (C-X-C motif chemokine receptor 4)
Diseases named in the same sentence as CXCR4 in open-access papers (continued):
Sharing a sentence is not in itself a finding about the gene and the disease.
ovarian carcinoma (continued). "Importantly, it has been shown that disruption of the CXCR4/CXCL12 axis using CXCR4-specific RNAi or a small molecule inhibitor of CXCR4 AMD3100 led to a decreased tumor vessel density and markedly reduced tumor angiogenesis in a FVB/NJ immunocompetent model of ovarian cancer." (PMID 24384839, 2013). "Because CCR1, CCR10 and CXCR4 are not specific receptors for the proinflammatory chemokines released by ovarian cancer cells, these receptors are likely to interact with chemokines released by other cell types such as immune cells and endothelial cells to the microenvironment." (PMID 23300534, 2012). "Collectively, these results suggest that attenuation of BRMS1 may play a critical role in promoting migration, invasion and angiogenesis of ovarian cancer cells and BRMS1 may regulate the metastatic potential at least in part through upregulation of CXCR4 via NF-κB activation." (PMID 22200669, 2012). "In addition, downregulation of CXCR4 and CXCL12 and inhibition of chemotaxis and chemoinvasion in breast and ovarian cancer cells toward CXCL12 are among of the biological effects of genistein likely through the inhibition of the estrogen dependent CXCL12 mRNA synthesis." (PMID 20049170, 2010). "Thus, a “cross-talk” between CXCL12/CXCR4 and EGFR intracellular pathways may link signals of cell migration and proliferation in ovarian cancer." (PMID 20049170, 2010). "In addition, we found metapristone was capable of greatly reducing expressions of CXCR4 to interrupt the SDF-1/CXCR4 chemokine axis and the related downstream signaling pathways, resulting in inhibition of cell proliferation, migration, invasion and functional adhesion of ovarian cancer." (PMID 31151472, 2019). "Interestingly, since the axis CXCR4/SDF1 has been described as an important element for the apoptosis inhibition mediated by TIMP1, we hypothesize that both TIMP1 and CXCR4 expression in CTCs from ovarian cancer patients could be playing an important role for avoiding apoptosis phenomena." (PMID 32423054, 2020). "Additionally, non-significant higher expression of CXCR-4 in ovarian tissue of Iranian patients with malignant cancer in comparison to those with benign cysts might be related to the probable role of this receptor in ovarian cancer promotion." (PMID 25999622, 2015). "Our preliminary study results showed a high expression of CXCR4 and CXCL12 in ovarian cancer tissues, but no expression in normal ovarian epithelial cells." (PMID 24765180, 2014).
glioma (194 papers, 2005 to 2025). A benign or malignant brain and spinal cord tumor that arises from glial cells (astrocytes, oligodendrocytes, ependymal cells). "Intriguingly, in glioma-bearing rats, FTY720 can internalize CXCR4 on glioma-associated microglia and macrophages in the tumor microenvironment to suppress the migration/invasion of C6 glioma cells by preventing MAPK-mediated IL-6 release." (PMID 38894892, 2024). "The MIF signaling axis on CD74/CXCR4 was found to be upregulated in glioma infiltrating macrophages and has been implicated in brain tumorigenesis by impeding microglial polarization." (PMID 38515213, 2024). "Our previous work confirmed that CXCR4 is closely related to the prognosis of glioma patients, but there are still some deficiencies." (PMID 37626511, 2023). "Like tumor-associated neutrophils, mast cells express the cytokine CXCR4, and they are present more largely in high-grade gliomas than in low-grade gliomas." (PMID 38275375, 2023). "Among the several molecular signaling pathways, the expression of SDF-1α/CXCR4 is also a key determinant of other glioma subtypes, causing devasting tumor progression and invasiveness." (PMID 36980182, 2023). "Glioma cell released SDF-1 causes GAMs that expresses CXCR4 to polarize towards a M2-like phenotype which is anti-inflammatory and pro-tumorigenic." (PMID 37790751, 2023). "Here, we, for the first time, identify that a circFGFR1 is a critical circRNA associated with the CXCR4 expression and glioma oncogenicity." (PMID 35059468, 2022). "As many other chemokine receptors, CXCR4 is overexpressed in glioma-initiating cells/GBM tissue and associated with a reduced PFS and OS." (PMID 34203660, 2021). "The marker genes for macrophage expression in glioma SPP1 and GPMB co-regulate with spot G enriching also other genes with impact for inflammation, among them CXCR4, related to glioma associated angiogenesis." (PMID 34206856, 2021). "Among its various functions, CXCR4 signaling is linked to glioma cell invasion, proliferation, tumor progression and angiogenesis." (PMID 34203660, 2021). "Directional perivascular invasion and association of glioma cells to existing blood vasculature rely on active CXCR4 signaling and downregulation of CXCR4 will prevent perivascular invasion, and delay tumor growth." (PMID 27863376, 2016). "When comparing glioma-associated macrophages/monocytes to naïve monocytes, only the expression of Il1rn, Tgfbi, and Cxcr4 was significantly higher." (PMID 25658639, 2015). "In this manuscript we provide evidence that CXCL12 signaling involved in chemotaxis of glioma cells is tightly linked to PDGFR signaling since inhibiting CXCR4 activation impairs PDGF-induced chemotaxis and vice versa." (PMID 24023874, 2013). "Glioma stem cells are associated with endothelial cells using the CXL12/CXCR4 axis." (PMID 34687436, 2022). "In the GL261 model a significant higher expression of all selected genes could be confirmed in glioma-associated macrophages/monocytes and for Il1rn, Clec7a, and Cxcr4 in glioma-associated microglia, compared to the respective control cells." (PMID 25658639, 2015). "Two recent studies have demonstrated the theranostic potential of CXCR4-targeted agents in high-grade gliomas." (PMID 40806525, 2025). "By establishing cutoff values for the Endothelial Score and CXCR4 expression, we categorized glioma patients into four distinct groups." (PMID 41041071, 2025). "CircFGFR1 upregulates CXCR4 expression in gliomas through hsa-miR-224-5p, which also plays a crucial role in tumor growth." (PMID 40722739, 2025). "CAR NK cells engineered with CXCR4 demonstrated chemotaxis toward CXCL12-producing gliomas, resulting in enhanced trafficking, tumor infiltration, and antitumor effects." (PMID 40895575, 2025).
glioma (continued). "Glioma cells overexpressing CXCR4 were treated with increasing doses of the compound, resulting in the inhibition of cell growth in a dose-dependent manner, especially in the U87 cell line, and in increase in apoptosis without apparent toxicity." (PMID 40142155, 2025). "Nevertheless, both studies are limited to preclinical or early-phase clinical stages, and key concerns such as off-target effects, long-term safety, and heterogeneous CXCR4 expression in gliomas remain to be fully addressed." (PMID 40806525, 2025). "Previous studies have also shown that U87 cells exhibit lower CXCR4 expression than other glioma cell lines, such as the LN428, LN308, and LN229 resulting in lower invasion capacity." (PMID 39715221, 2024). "For example, the Notch signaling pathway promotes invasion, self-renewal, and proliferation of glioma-starting cells via controlling the chemokine system CXCL12/CXCR4." (PMID 38203782, 2024). "The angiotensin II type 1 receptor/CXCR4/NF-κB signaling pathway is involved in glioma progression, and SOX9 is the downstream target of telmisartan." (PMID 39063232, 2024). "CXCL12 is also able to attract CXCR4 + myeloid derived suppressor cells to create an immunosuppressive microenvironment that favors the growth of glioma, as reported for other tumors." (PMID 38293652, 2023). "CXCL12 has higher affinity for the receptor CXCR7 whose high expression correlates with poor glioblastoma patient survival and similarly to CXCR4 activation, triggers glioma proliferation and invasion." (PMID 38293652, 2023). "CXCR4 antagonist (AMD3100) has been proposed as an anti-GBM therapeutic target that reduces the ability of glioma cell lines to survive and proliferate." (PMID 37626511, 2023). "As the differentiation degree of glioma increased, the expression level of CXCR4 decreased gradually, instead, the expression level of CXCR7 increased." (PMID 37153567, 2023). "We knocked down the expression of CXCR4 in glioma cell lines (U87 and U251) and used Western Blot to verify the knockdown effect." (PMID 37626511, 2023). "In glioma mice, combined therapy of anti-CXCR4 and anti-PD-1 reduced immunosuppressive leukocytes counts, advanced the CD4+/CD8+ T cell ratio and raised the amount of pro-inflammatory cytokines." (PMID 37790751, 2023). "Relatedly, it was demonstrated that miR-21 or CXCR4 inhibition, but especially their double-targeted knockdown, diminished migration, invasiveness, and proliferation, and enhanced apoptosis in glioma cells by suppressing the PI3K/AKT and Raf/MEK/ERK pathways." (PMID 36980182, 2023). "Beyond CXCR4, miR-21 has also been extensively identified as a key regulator in glioma malignancy through in vitro and in vivo tests." (PMID 36980182, 2023). "Although no significant change of net distance was observed in NSC (p = 0.32), antagonist for CXCR4 have blocked CXCL12‐mediated iPSC‐NSC pathotropism toward glioma cells." (PMID 37693056, 2023). "Our data showed that knockdown of CXCR4 significantly reduced the level of inflammation in glioma cells, suggesting a positive correlation between CXCR4 and tumor cell inflammation in GBM." (PMID 37626511, 2023). "Chemokine receptor-4 (CXCR4) is highly expressed in different cancers, including gliomas, and is related to the neo-angiogenesis, migration, and survival of malignant cells." (PMID 37835806, 2023). "One study found that in human glioma cell lines and primary tumors, CXCR4 expression correlated directly with malignancy." (PMID 39355049, 2023). "Previously, it was also reported that interstitial fluid flow increased glioma and hepatocellular carcinoma cell invasion via CXCR4-dependent signaling by increasing CXCR4 levels." (PMID 36863017, 2023). "Recent data has proved that glioma tumor stem-like cells support tumor angiogenesis and vasculogenesis via the CXCR4." (PMID 36980182, 2023).
glioma (continued). "Together, our findings hinted that the circFGFR1-induced hsa-miR-224-5p sponge was the culprit of elevated CXCR4 abundance and aggravated malignant behaviors in glioma cells." (PMID 35059468, 2022). "Targeting MDSCs with CXCR4 blockade potentiated anti-PD-1 to uphold antitumor immune reactions and ameliorated OS in glioma cell-bearing mice." (PMID 34980128, 2022). "The TIL population and activation in the glioma microenvironment were also sustained by dual targeting CXCR4 and PD-1." (PMID 35337133, 2022). "It was easily found that the level of CXCR4 in glioma cells was higher than NHA cells, and the abundance of CXCR4 was positively correlated with the circFGFR1 level in glioma cell lines." (PMID 35059468, 2022). "Our findings, first time, identify that circFGFR1 promotes glioma malignancy through hsa-miR-5p/CXCR4 signaling." (PMID 35059468, 2022). "Cell surface chemokine receptor (CXCR4) is involved in the proliferation, invasion, migration, angiogenesis, and metastasis in different tumors, including glioma." (PMID 35059468, 2022). "The hsa-miR-224-5p expression is negatively corrected with the glioma malignancy through inhibiting CXCR4 level." (PMID 35059468, 2022). "High expression of CXCR4 in glioma was modulated through Akt/mTOR signaling by Notch1, which promotes the migration of glioma-originating cells." (PMID 35571062, 2022). "Despite many reports focused on the molecular mechanism of CXCR4, the circRNA-induced CXCR4 regulation is still limited to be known in glioma." (PMID 35059468, 2022). "Taken together, our findings suggest that circFGFR1 plays a critical role in the tumorigenic behaviors in glioma cells by upregulating CXCR4 expression via sponging to hsa-miR-224-5p." (PMID 35059468, 2022). "Glioma infiltration of the subventricular zone is also related to C-X-C motif chemokine receptor type 4 (CXCR4)/C-X-C motif chemokine ligand 12 (CXCL12 or stromal derived factor-1, SDF-1)." (PMID 35204054, 2022). "To further confirm the role of hsa-miR-224-5p in circFGFR1-induced CXCR4 regulation and glioma progression, we generated hsa-miR-224-5p knockout SNB19 cell line by using CRISPR/Cas9 with RNP system." (PMID 35059468, 2022). "Dual targeting CXCR4 and PD-1 also sustained the TILs population as well as their activation in the glioma microenvironment." (PMID 34980128, 2022). "In glioma cell-bearing mice, targeting MDSCs with CXCR4 inhibition potentiated anti-PD-1 to maintain anticancer immune reactivity and improved OS." (PMID 35337133, 2022). "MFAP2 expression was also correlated with chemokine receptors in gliomas, such as CCR3, CCR7, CXCR4, and CXCR6, which were significantly associated with MFAP2 expression in both LGG and GBM." (PMID 36204318, 2022). "Together, those findings stated that CXCR4 was obbligato and responsible for circFGFR1-induced glioma progression regulation." (PMID 35059468, 2022). "Using U87-MG intracranial xenografts, inhibitors of CXCR4 signaling such as peptide R and Plerixafor modulated the TAMs towards an anti-tumorigenic phenotype and inhibited the growth of glioma cells in vitro." (PMID 35967394, 2022). "Co-expression of HIF-1α, which plays a critical role in GBMs progression, and CXCR4 was observed in hypoxic regions of tumor, i.e., pseudopalisading glioma cells." (PMID 34200145, 2021). "AMD3100, also known as plerixafor, is an FDA-licensed CXCR4 antagonist which inhibited migration of glioma cells in vitro under normoxic and hypoxic conditions." (PMID 34203660, 2021). "Representatively, the chemoattractant molecules responsible for the myeloid cell migration to the glioma, for example, CSF-1R, avβ3/5 integrins, and CXCR4 are being targeted in multiple trials." (PMID 34084145, 2021). "Studies of glioma showed that bradykinin, CXCR4, and Wnt7 were involved in glioma spread along vessels." (PMID 34249699, 2021).
glioma (continued). "Currently, [68Ga]pentixafor serves as an important PET radiotracer for CXCR4-specific detection at the clinical level to diagnose certain cancers such as multiple myeloma and glioma." (PMID 34500609, 2021). "AMD3100, a well-known CXCR4 inhibitor, reduced vessel density and tumor growth in both rat and mouse glioma models." (PMID 34203660, 2021). "In the last two decades, extensive evidence has proven CXCR4 as significantly related to glioma malignancy." (PMID 35008294, 2021). "For instance, in 2016, a clinical study was conducted using 14 in 15 patients with glioma to enable the detection of CXCR4, and the imaging results were compared with that of O-(2-18F-fluoroethyl)-L-tyrosine ([18F]FET)-PET." (PMID 34500609, 2021). "This review also highlights ACKR3 as a multifaceted player in almost every of these glioma-related cellular processes and subtypes and prompts researchers in the field to further apprehend the subtleties of the CXCR4/ACKR3/CXCL12 triad in glioma." (PMID 35008294, 2021). "Given the discernible expression of ACKR3 in MVP areas of GBM tumors, its contribution to the angiogenic mechanisms in glioma patients and its interplay with CXCR4 definitely warrant further investigation." (PMID 35008294, 2021). "Knockdown of either miR-21 or CXCR4 decreased glioma proliferation, invasion, and migration and enhanced apoptosis." (PMID 33123586, 2020). "We constructed miR-21 knockdown (anti-miR-21), CXCR4 knockdown (sh-CXCR4), and miR-21 and CXCR4 double-targeted knockdown (anti-miR-21 + sh-CXCR4) U87 and U251 cells to investigate the anti-miR-21 + sh-CXCR4 generated effects on glioma tumorgenicity." (PMID 33123586, 2020). "Currently, miR-21 and CXCR4 are being extensively investigated as two key regulators in glioma malignancy." (PMID 33123586, 2020). "Double-targeted knockdown of miR-21 and CXCR4 was performed in glioma cell lines (U87 and U251), and its effects on glioma malignant progression were evaluated in cells and xenograft mouse models." (PMID 33123586, 2020). "Previous studies have demonstrated that the overexpression of the chemokine-4 receptor (CXCR4) results in increased migration of glioma tumor cells." (PMID 32410920, 2020). "To better illustrate the roles of miR-21 and CXCR4 together in tumor growth of glioma, we employed a U87 xenograft mouse model." (PMID 33123586, 2020). "Numerous studies suggest that the overexpression of CXCR4 facilitates proliferation, angiogenesis, invasion, and metastasis, as well as chemotherapy and radiotherapy resistance of glioma in several glioma cell lines and mouse models." (PMID 33123586, 2020). "This revealed the potent repressive effects of anti-miR-21 + sh-CXCR4 on invasion and migration capabilities of glioma cells." (PMID 33123586, 2020). "Preclinical studies of N-[11C]methyl-AMD3465 PET ligand have also demonstrated the feasibility of obtaining in vivo images of CXCR4 expression in glioma tumors." (PMID 32410920, 2020). "CXCR4 is another factor that plays a vital role in glioma pathology (i.e., neoplastic transformation, malignant tumor progression, infiltration, metastasis, angiogenesis, and vasculogeneis)." (PMID 33123586, 2020). "In the current study, we demonstrated that glioma patients expressed aberrant EZH2 and CXCR4 levels and that these levels were significantly associated with patient survival according to GEPIA." (PMID 32635336, 2020). "It is therefore conceivable that FTY720 can target the glioma microenvironment by inhibiting microglial MAPK-mediated IL-6 secretion downstream of CXCR4 internalization." (PMID 32194542, 2020). "Since it is well known that CXCL12 activates members of the MAP kinase family in gliomas via its G-protein-coupled receptors CXCR4 and CXCR7, it seems obvious that CXCL12 regulated CCL2 and SAA2 expression during cellular dormancy entry via these pathways." (PMID 32346064, 2020).